TRBV12-4 (T cell receptor beta variable 12-4)
Description:
V region of the variable domain of T cell receptor (TR) beta chain that participates in the antigen recognition. Alpha-beta T cell receptors are antigen specific receptors which are essential to the immune response and are present on the cell surface of T lymphocytes. Recognize peptide-major histocompatibility (MH) (pMH) complexes that are displayed by antigen presenting cells (APC), a prerequisite for efficient T cell adaptive immunity against pathogens. Binding of alpha-beta TR to pMH complex initiates TR-CD3 clustering on the cell surface and intracellular activation of LCK that phosphorylates the ITAM motifs of CD3G, CD3D, CD3E and CD247 enabling the recruitment of ZAP70. In turn ZAP70 phosphorylates LAT, which recruits numerous signaling molecules to form the LAT signalosome. The LAT signalosome propagates signal branching to three major signaling pathways, the calcium, the mitogen-activated protein kinase (MAPK) kinase and the nuclear factor NF-kappa-B (NF-kB) pathways, leading to the mobilization of transcription factors that are critical for gene expression and essential for T cell growth and differentiation. The T cell repertoire is generated in the thymus, by V-(D)-J rearrangement. This repertoire is then shaped by intrathymic selection events to generate a peripheral T cell pool of self-MH restricted, non-autoaggressive T cells. Post-thymic interaction of alpha-beta TR with the pMH complexes shapes TR structural and functional avidity.
Synonyms: TRBV124; TCRBV12S4; TCRBV8S2A1T
Gene: T-cell receptor variable (V) gene on chromosome 7 (142,563,740 to 142,564,245, forward strand). Ensembl gene ENSG00000276953.
Subcellular location: Cell membrane
Gene Ontology:
Biological process: cell surface receptor signaling pathway
Cellular component: plasma membrane
Homologues: Orthologues: mouse Trbv15 (63% identical). Paralogues in human: TRBV12-3 (97% identical), TRBV12-5 (70% identical), TRBV7-6 (58% identical), TRBV7-2 (57% identical), TRBV7-7 (57% identical), TRBV7-3 (57% identical), TRBV14 (55% identical), TRBV17 (55% identical), TRBV7-4 (55% identical), TRBV7-9 (55% identical), TRBV11-2 (54% identical), TRBV11-3 (53% identical), and 39 more.